SIRT1 (sirtuin 1)
Diseases named in the same sentence as SIRT1 in open-access papers (continued):
Sharing a sentence is not in itself a finding about the gene and the disease.
Obesity (continued). "Hitherto known to be an essential factor for the control of longevity and healthy ageing, SIRT1 appears to also function as fundamental epigenetic conduit that links obesity and nutritional status with changes in pubertal timing." (PMID 30305620, 2018). "Specific genetic ablation of SIRT1 in WAT leads to obesity, increased inflammatory infiltration, and insulin resistance similar to that observed in HFD induced obesity, further suggesting SIRT1 deficiency leads to whitening effects of mature adipocytes." (PMID 30186237, 2018). "Our present study unveiled a novel role of the SRT1720-induced pharmacological activation of Sirt1 in protecting against the progression of obesity-related impaired angiogenesis and glucose intolerance." (PMID 30054532, 2018). "The leptin-induced protective mechanisms against obesity are dependent on SIRT1 in the POMC neurons." (PMID 30532738, 2018). "SIRT1 is known to play a crucial role in cancers, obesity, stroke, and dementia along with regulation of metabolism and the modulation of metabolic diseases." (PMID 32149160, 2018). "In fact, experimental evidence of SIRT1 overexpression suggests that a decrease in serum insulin and cholesterol occurs in addition to that of adipose tissue volume and obesity-induced insulin resistance." (PMID 30367115, 2018). "Accumulating evidence suggests that Sirt1/dSir2 play important roles not only in aging but also in lipid metabolism and obesity." (PMID 29484111, 2018). "Resveratrol, a polyphenol from several plants, has showed beneficial effect on obesity, diabetes and cardiovascular disease as a SIRT1 activator." (PMID 30563192, 2018). "Mentioned briefly above, SIRT1 in SF1 neurons is required for the defense against dietary-induced obesity." (PMID 30532738, 2018). "In conclusion, circulating SIRT1 inversely parallels the entire spectrum of fat phenotype, basal metabolic rate, inflammatory status, and eating behavior from anorexia to obesity through normal weight." (PMID 30131769, 2018). "Neuron-specific knockout of SIRT1 within the forebrain reversed obesity-induced hippocampal-dependent spatial memory deficits." (PMID 30416425, 2018). "A previous study indicated that obesity and inflamation induced the cleavage of SIRT1 protein in adipose tissue and differentiated 3T3-L1 cells by caspase-1." (PMID 29050301, 2017). "All of these types of stress stimuli are involved in SIRT1-regulated physiological and pathological events such as chronic inflammatory diseases and metabolic dysfunctions, including ageing, obesity, diabetes, and cancer." (PMID 29133780, 2017). "To further investigate the mechanism by which zerumbone regulates the miR-146b/SIRT1 axis to reduce obesity and adipogenesis, we analyzed its effect on the acetylation of FOXO1 and PGC1-α, two downstream targets of SIRT1." (PMID 28445161, 2017). "The SIRT1 pathway is a key regulator of metabolism and is an emerging target for the treatment of obesity." (PMID 28287466, 2017). "Sirt1 activation has beneficial health consequences such as improved insulin sensitivity, obesity reduction, increased mitochondrial function, decreased glucose levels, and increased physiological functions." (PMID 28592311, 2017). "In conclusion, our study demonstrates that miR-377 functions as a novel inhibitor of SIRT1 in obesity-induced inflammation and insulin-resistance." (PMID 29050301, 2017). "Taken together, these results demonstrated that miR-377 expression is increased under conditions of inflammation and HFD-induced obesity in an effect that is negatively correlated with SIRT1 expression." (PMID 29050301, 2017). "Sirt1 activating compounds such as SRT1720 protect against obesity and glucose intolerance, but the mechanism by which they confer these health benefits has been unclear." (PMID 28396013, 2017). "In this study, we attempted to identify a new compound involved in the miR-146b/SIRT1 pathway, and found that zerumbone is a candidate for prevention of obesity." (PMID 28445161, 2017).
Obesity (continued). "In conclusion, our findings suggest that miR-377 promotes white adipose tissue inflammation and decreases insulin sensitivity in obesity, at least in part, through suppressing SIRT1." (PMID 29050301, 2017). "Zerumbone supplementation increased SIRT1 activity, ameliorated HF-induced obesity, and reduced HF-induced WAT hypertrophy and hyperplasia in C57BL/6N mice." (PMID 28445161, 2017). "SIRT1 activation results in beneficial effects in metabolic disorders involving obesity, type 2 diabetes, and cardiovascular disease." (PMID 28445161, 2017). "We suggest that Creb/Crtc2 negatively regulates the Sirt1/Pparα/Fgf21 axis via the induction of miR-34a under diet-induced obesity and insulin-resistant conditions." (PMID 29192248, 2017). "The intersection of these two pathways has recently emerged in studies demonstrating the importance of SIRT1 in the protective actions of HO-1 induction in the liver in two different models of dietary-induced obesity with fatty liver disease." (PMID 28287466, 2017). "Activation of SIRT1 in the liver of both diet- and obesity-induced T2DM mice strongly attenuated UPR activation by decreasing eIF2-α phosphorylation, XBP-1splicing, and CHOP expression." (PMID 28521305, 2017). "More precisely, inactivation of AMPK in POMC neurons induced obesity while SIRT1 in POMC neurons is required for adaptations against diet-induced obesity." (PMID 28424580, 2017). "Increased expressions of phosphorylated AMPK and Sirt1 regulate lipid homeostasis and glucose metabolism, consequently preventing fat accumulation in liver and ameliorating obesity-related metabolic changes." (PMID 28686680, 2017). "Previously, we demonstrated that inhibition of miR-146b alleviates diet-induced obesity through SIRT1 regulation." (PMID 28445161, 2017). "In the same way, manipulation of cellular NAD levels by pharmacological inhibition of other NAD-consuming enzymes results in activation of SIRT1 and protection against obesity-related pathologies." (PMID 26788256, 2016). "In obesity, with increased number and size of adipocytes, there is a decrease in SIRT1 levels and activity." (PMID 26904696, 2016). "Together, these data support that, like obesity with low SIRT1, acute trauma generates an inflammatory reaction in which insufficiently available SIRT1 leads to excessive inflammatory injury if an acute infection occurs." (PMID 26904696, 2016). "Crujeiras and colleagues assessed SIRT1 expression in peripheral blood mononuclear cells to investigate the effect of the sirtuin pathway on obesity therapy." (PMID 27123454, 2016). "Compared with SIRT1, knowledge about the role of other SIRTs in the pathogenesis of obesity is relatively limited." (PMID 27104517, 2016). "In vitro studies have shown that in one of the known SIRT1-targeting miRNAs, miR-34a is up-regulated in murine liver, in response to obesity." (PMID 27104517, 2016). "In an animal model, dietary gallic acid protected mice from diet-induced obesity by stimulating the AMPKα/Sirt1/PGC1α pathway in liver, muscle, and brown adipose tissues." (PMID 27340504, 2016). "Genetic deletion and also pharmacological inhibition of the protein CD38, the main NAD glycohydrolase in mammalian tissues, activate SIRT1 and protect against obesity and metabolic syndrome." (PMID 26788256, 2016). "Understanding the role and mechanisms of natural products in Sirt1 regulation is crucial for the discovery and development of pharmacological agents for potential use in the clinical management of obesity." (PMID 27669202, 2016). "As SIRT1 is a closely related factor to AMPKα in obesity, we assessed the effects of VN on AMPKα and its upstream and downstream targets, LKB1 and ACC." (PMID 27143989, 2016). "The elevated SIRT1 expression suggested the effects of VN on the SIRT1-AMPKα axis, which is a key factor in the etiology of obesity." (PMID 27143989, 2016).
Obesity (continued). "This shows that age and obesity-related decline in ARC SIRT1 function contributes to a disruption of energy homeostasis." (PMID 27104517, 2016). "Null mutants for sir2 display increased levels of stored lipid, analogous to the role of SIRT1 in suppressing obesity." (PMID 27058248, 2016). "If the relevance of our findings is confirmed in humans, then a better understanding of the molecular mechanisms involved in SIRT1/c-Myc signaling pathways should lead to the development of new therapeutic strategies for obesity." (PMID 26655722, 2016). "Recently, studies performed on animal models reported that maternal high fat diet and obesity resulted in a decrease of SIRT1 mRNA in fetal livers, highlighting the role of intrauterine environment on SIRT1 expression." (PMID 26890260, 2016). "The NAD+-dependent deacetylase SIRT1 has been shown to maintain proper metabolic functions in many tissues to protect against obesity." (PMID 26655722, 2016). "Another mechanism by which AGE-induced obesity was proposed was by suppression of survival factor called sirtuin 1 (SIRT1), this factor helps in mobilization of fatty acids and it was lower in mice on high-MG diet." (PMID 26690206, 2015). "The role of SIRT1 as a regulator of lipid metabolism integrates several metabolic research focus areas, including obesity, diabetes, hepatic steatosis, and cancer." (PMID 25569080, 2015). "SIRT1 deletion in hepatocytes impaired the activity of PPARα, resulting in development of hepatic steatosis, whereas SIRT1 hepatic overexpression suppressed the expression of gluconeogenic genes and attenuated obesity-induced ERS." (PMID 26539534, 2015). "SIRT1 expression or activity has been shown to be reduced or inhibited in obesity or after palmitate exposure." (PMID 26075729, 2015). "Because there is no single reliable marker for SIRT1 function in vivo, here I discuss changes in NAD+ content and SIRT1 protein levels during aging and diet-induced obesity in the hypothalamus." (PMID 26236282, 2015). "Again, it is shown that, in contrast to that in a starved state or caloric restriction, SIRT1 signaling is decreased, and blood adiponectin levels decreased, due to oxidative stress and inflammation, in obesity." (PMID 28721260, 2015). "Over-expression of SIRT1 in the mouse forebrain was also shown to result in obesity, impaired glucose tolerance and some defects in motor function." (PMID 25805970, 2015). "While an increased phosphorylation of SIRT1 is found under CR conditions and a decreased activity is found in obesity, it has a limited role in CR's antitumor effect." (PMID 25026276, 2014). "In mice with diet-induced obesity, treatment with resveratrol, which is an activator of Sirt1, significantly increases mitochondrial biogenesis and protects against metabolic disorders." (PMID 24614171, 2014). "ARC SIRT1 is a negative regulator of energy balance, and decline in ARC SIRT1 function contributes to disruption of energy homeostasis by ageing and diet-induced obesity." (PMID 24374551, 2014). "Clarifying the detailed mechanisms that regulate ARC SIRT1 protein in the context of ageing and diet-induced obesity is our next goal." (PMID 24374551, 2014). "Hepatic mRNA expression of circadian (CLOCK, BMAL1, REV-ERBα, CRY, PER) and metabolic (PPARα, SIRT1) genes were strongly suppressed in offspring exposed to both maternal obesity and HFD." (PMID 24416203, 2014). "Accumulated evidence has revealed that SIRT1 is crucial for caloric restriction-induced longevity, and SIRT1 genetic variation is related to obesity, suggesting that SIRT1 is a key regulator of whole-body energy balance." (PMID 25330910, 2014). "Sirt1 was recently shown to repress the onset of diet-induced obesity by promoting mitochondrial FA oxidation through activating peroxisome proliferator-activated receptor α (PPARαα and its coactivator PGC-1α." (PMID 24614171, 2014).
Obesity (continued). "Galanin receptors and SIRT1 are known to reverse obesity-induced downregulation of UCP1 expression in WAT." (PMID 24624222, 2014). "Resveratrol was identified as a Sirt1 activator and gained interest in a number of pathological settings—among them obesity." (PMID 23819014, 2013). "The genetic overexpression of SIRT1 has also been shown to protect mice from obesity-promoted hepatocarcinogenesis, suggesting that SIRT1 is a potential molecular target for dietary and therapeutic agents against HCC development." (PMID 24379011, 2013). "SIRT1 activation is recognized to protect against obesity-induced hepatic steatosis and inflammation." (PMID 24379011, 2013). "SIRT1 activation is recognized to protect against obesity-induced glucose intolerance, insulin resistance, hepatic steatosis, inflammation, and carcinogenesis." (PMID 24379011, 2013). "Nevertheless, several other factors including diabetes and obesity have been reported to modulate Sirt1 activity." (PMID 23844973, 2013). "In conclusion, these results suggest that miR-146b is a new SIRT1 inhibitor and potential molecular target for the development of novel therapeutic strategies against obesity." (PMID 24009212, 2013). "We identified miR-146b as a new regulator of adipogenesis and characterized the miR-146b/SIRT1 pathway as a potential target for preventing and treating obesity." (PMID 24009212, 2013). "Similar findings were observed in transgenic mice over-expressing SIRT1 that were protected against obesity dependent impaired glucose tolerance." (PMID 22761194, 2012). "To further explore the role of myeloid SIRT1 in regulation of ATM phenotypic switch in obesity-induced inflammation, we put MSKO and their fl/fl littermates on HF diets." (PMID 23183898, 2012). "It has previously been shown that levels of Sirt1 mRNA and SIRT1 activity are decreased in an animal obesity model and in obese humans." (PMID 23137106, 2012). "We previously demonstrated that AMPK and SIRT1 can detect excess nutrients in diet-induced obesity and serve as negative regulators of nutrient stress-induced inflammation." (PMID 23071533, 2012). "To investigate the potential consequences of decreased SIRT1, we utilized db/db mice, a genetic model of obesity and insulin resistance resulting from a leptin receptor mutation." (PMID 23137106, 2012). "Further, activation of SIRT1 using a synthetic molecule protects mice from diet-induced obesity and increases lipid oxidation in the skeletal muscle by mediating the deacetylation of PGC1α and FOXO1." (PMID 23024761, 2012). "For example, POMC-neuron-specific SIRT1 knockout mice display hypersensitivity to diet-induced obesity; a defect brought on by reduced sympathetic nerve activity and brown adipocytes content selectively in one visceral fat depot: the perigonadal fat." (PMID 21464518, 2011). "Knockout of SIRT1 in pro-opiomelanocortin (POMC) neurons caused reduced energy expenditure in mice and then hypersensitivity to diet-induced obesity." (PMID 21738790, 2011). "If this prediction is true, in addition to be a key molecular component of defensive mechanisms against diet-induced obesity SIRT1 in POMC neurons will also need to be considered as a critical regulator of lifespan." (PMID 21464518, 2011). "Although the notion of a direct role for SIRT1 and its sisters in extending life span has come into question recently, they clearly suppress age-dependent pathologies, reducing diabetes, obesity, neurodegeneration, etc.." (PMID 22064828, 2011). "Given the role of Sirt1 in several peripheral tissues and hypothalamus, therapies centered on Sirt1 present promising results for the treatment of metabolic diseases such as obesity." (PMID 20020036, 2009).
Obesity (continued). "Given that increased levels of nicotinamide adenine dinucleotide (NAD) via deletion of CD38 have been shown to prevent high fat diet induced obesity in mice in a SIRT-1 dependent fashion we explored the possibility of directly applying NAD to zebrafish." (PMID 18752667, 2008). "SIRT1 expression is reduced in metabolic disorders and in complicated diseases such as obesity." (PMID 42075052, 2026). "RT-qPCR results showed that, compared with the control group, mRNA expression levels of VEGFA, VEGFR-2, CD31, and SIRT1 were significantly decreased in the obesity group (P < 0.001), while the expression levels of GLUT1, HIF-1α, TNF-α, IL-6, HMGB1, and TLR4 were significantly upregulated (P < 0.01)." (PMID 41505418, 2026). "In obesity, SIRT1 expression in adipose tissue is significantly suppressed." (PMID 41510997, 2026). "Collectively, these findings suggest that reduced AMPK and SIRT1 activity in patients with asthma and obesity may contribute to impaired corticosteroid responsiveness." (PMID 41376865, 2025). "This study substantiates the potential of RRTFB as a phytochemo therapeutic strategy for combating obesity, highlighting its ability to mitigate obesity through DNMT3a/SIRT1‐mediated epigenetic regulation, with flavonoids identified as the primary bioactive components." (PMID 40909259, 2025). "We further explored whether estradiol can alleviate obesity‐induced muscle dysfunction mediated by the SIRT1–NAMPT pathway." (PMID 39901373, 2025). "This study aimed to explore the effects of high-intensity interval training (HIIT) on hippocampal neuronal damage, cognitive function, and the SIRT1/PGC1α pathway in obese rats and provide a theoretical basis for HIIT intervention in improving CI caused by obesity." (PMID 41140914, 2025). "Similarly, we observed a reduction in the levels of Sirt1, consistent with several reports demonstrating that this deacetylase is upregulated in fasting conditions and reduced in obesity." (PMID 40806011, 2025). "Previous studies found that activating AMPK/SIRT1 pathway protects against HFD-induced obesity and may be considered as a protective effect for the management of obesity and associated metabolic complications." (PMID 40050385, 2025). "Moreover, the 17β‐estradiol alleviates the muscle abnormality by the SIRT1–NAMPT deacetylation pathway, providing insights into sex differences in obesity‐associated OSA." (PMID 39901373, 2025). "The mechanisms underlying adropin's role in obesity are still under investigation, and it may exert its effects via multiple signaling pathways, including AMPK, PPARγ, and Sirtuin 1 (SIRT1)." (PMID 41211169, 2025). "Rosa roxburghii Tratt fermentation broth alleviates obesity via DNMT3a/SIRT1 axis." (PMID 40909259, 2025). "Furthermore, the complex interplay between SIRT1 and obesity in patients with PAH warrants further investigation." (PMID 41011644, 2025). "SIRT1 levels have been found to decrease in diet‐induced obesity in rodents." (PMID 39980831, 2025). "This suggests that RRTFB may significantly alleviate obesity and related chronic diseases by altering the methylation status of epididymal fat SIRT1." (PMID 40909259, 2025). "Tissue-specific knockout models for AMPKα1/α2, SIRT1, or PGC-1α can delineate causal roles in immunometabolic remodeling, while disease-specific animal models (e.g., high-fat diet–induced obesity, streptozotocin-induced diabetes, or APP/PS1 Alzheimer’s models) can evaluate physiological relevance." (PMID 41573560, 2025). "Indeed, SIRT1 knock-out mice exhibit obesity, insulin resistance, hepatic lipid accumulation, and inflammation." (PMID 41415839, 2025). "The polymorphic variants rs12778366 and rs7895833 in the SIRT1 gene promoter region, according to few studies, are associated with age-related macular degeneration (AMD), type 2 diabetes mellitus (T2DM), obesity, glucose tolerance, the risk of hypertension, and PE." (PMID 40243583, 2025).